FGFR3 (fibroblast growth factor receptor 3)
Description:
Tyrosine-protein kinase that acts as a cell-surface receptor for fibroblast growth factors and plays an essential role in the regulation of cell proliferation, differentiation and apoptosis. Plays an essential role in the regulation of chondrocyte differentiation, proliferation and apoptosis, and is required for normal skeleton development. Regulates both osteogenesis and postnatal bone mineralization by osteoblasts. Promotes apoptosis in chondrocytes, but can also promote cancer cell proliferation. Required for normal development of the inner ear. Phosphorylates PLCG1, CBL and FRS2. Ligand binding leads to the activation of several signaling cascades. Activation of PLCG1 leads to the production of the cellular signaling molecules diacylglycerol and inositol 1,4,5-trisphosphate. Phosphorylation of FRS2 triggers recruitment of GRB2, GAB1, PIK3R1 and SOS1, and mediates activation of RAS, MAPK1/ERK2, MAPK3/ERK1 and the MAP kinase signaling pathway, as well as of the AKT1 signaling pathway. Plays a role in the regulation of vitamin D metabolism. Mutations that lead to constitutive kinase activation or impair normal FGFR3 maturation, internalization and degradation lead to aberrant signaling. Over-expressed or constitutively activated FGFR3 promotes activation of PTPN11/SHP2, STAT1, STAT5A and STAT5B. Secreted isoform 3 retains its capacity to bind FGF1 and FGF2 and hence may interfere with FGF signaling.
Synonyms: CD333; JTK4; CEK2; ACH; HSFGFR3EX
Tractability: Small molecule: an approved drug acts on it; a structure with a bound ligand is known; a high-quality ligand is known; it belongs to a druggable protein family. Antibody: a drug acting on it is in phase 1 trials; its Gene Ontology location is reachable by antibodies, with high confidence; UniProt places it where antibodies can reach, with medium confidence; UniProt predicts a signal peptide or a membrane-spanning region. PROTAC: UniProt records ubiquitination sites on it; ubiquitination databases record sites on it; a small molecule that binds it is known. Other modalities: a drug acting on it is in phase 2 or 3 trials.
Target class: Enzyme; Tyrosine protein kinase FGFR family; Protein Kinase; Kinase; TK protein kinase group
Chemical probes: AZD-4547 (high quality), FIIN-1 (high quality), FIIN-2 (high quality), FIIN-3 (high quality), INFIGRATINIB (high quality), PD134445, PD134446, PD134447, PD134448, PD134449, PD134450
Gene: Protein-coding gene on chromosome 4 (1,793,286 to 1,808,873, forward strand). Ensembl gene ENSG00000068078.
Subcellular location: Cell membrane (Isoform 1); Cytoplasmic vesicle; Endoplasmic reticulum; Cell membrane (Isoform 2); Secreted (Isoform 3); Cell membrane (Isoform 4)
Subcellular location (Human Protein Atlas): Endoplasmic reticulum; Predicted to be secreted
Pathways (Reactome):
Signal Transduction: FGFR3b ligand binding and activation; FGFR3c ligand binding and activation; FRS-mediated FGFR3 signaling; Negative regulation of FGFR3 signaling; PI-3K cascade:FGFR3; PI3K Cascade; PI5P, PP2A and IER3 Regulate PI3K/AKT Signaling; PIP3 activates AKT signaling; Phospholipase C-mediated cascade; FGFR3; RAF/MAP kinase cascade; SHC-mediated cascade:FGFR3
Disease: Constitutive Signaling by Aberrant PI3K in Cancer; Signaling by FGFR3 fusions in cancer; Signaling by FGFR3 in disease; Signaling by activated point mutants of FGFR3; t(4;14) translocations of FGFR3
Gene Ontology:
Molecular function: fibroblast growth factor binding; fibroblast growth factor receptor activity; identical protein binding; protein binding; protein tyrosine kinase activity; ATP binding; protein kinase activity; transmembrane receptor protein tyrosine kinase activity
Biological process: cell surface receptor signaling pathway via JAK-STAT; fibroblast growth factor receptor apoptotic signaling pathway; fibroblast growth factor receptor signaling pathway; positive regulation of cell population proliferation; positive regulation of ERK1 and ERK2 cascade; positive regulation of MAPK cascade; positive regulation of phosphatidylinositol 3-kinase/protein kinase B signal transduction; positive regulation of phospholipase activity; positive regulation of tyrosine phosphorylation of STAT protein; bone maturation; bone mineralization; bone morphogenesis; chondrocyte differentiation; chondrocyte proliferation; endochondral bone growth; endochondral ossification; MAPK cascade; negative regulation of developmental growth; skeletal system development; cartilage development; ossification
Cellular component: endoplasmic reticulum; Golgi apparatus; plasma membrane; transport vesicle; focal adhesion; receptor complex; cytoplasmic vesicle; extracellular region; membrane
Genetic constraint (gnomAD): Loss-of-function variants: 24 observed, 73.63 expected, observed/expected ratio (o/e) 0.33, 90% interval 0.23 to 0.46. The synonymous counts are far from expectation, so gnomAD's model fits this gene poorly and the ratio says little. Missense variants: 972 observed, 1,079.6 expected, observed/expected ratio (o/e) 0.9, 90% interval 0.85 to 0.95. Synonymous variants: 600 observed, 476.9 expected, observed/expected ratio (o/e) 1.26, 90% interval 1.18 to 1.35.
Gene-disease validity (ClinGen):
ClinGen rates the evidence that FGFR3 causes each of these diseases.
achondroplasia (autosomal dominant): Definitive. Achondroplasia is the most common form of chondrodysplasia, characterized by rhizomelia, exaggerated lumbar lordosis, brachydactyly, and macrocephaly with frontal bossing and midface hypoplasia.
Crouzon syndrome-acanthosis nigricans syndrome (autosomal dominant): Definitive. Crouzon syndrome with acanthosis nigricans (CAN) is a very rare, clinically heterogeneous form of faciocraniostenosis with Crouzon-like features and premature synostosis of cranial sutures (Crouzon disease), associated with acanthosis nigricans (AN).
hypochondroplasia (autosomal dominant): Definitive. Hypochondroplasia is characterized by disproportionate short stature, mild lumbar lordosis and limited extension of the elbow joints.
Muenke syndrome (autosomal dominant): Definitive. Muenke syndrome is a syndromic craniosynostosis with significant phenotypic variability, usually characterized by coronal synostosis, midfacial retrusion, strabismus, hearing loss and developmental delay.
thanatophoric dysplasia (autosomal dominant): Definitive. A primary bone dysplasia with micromelia characterized by macrocephaly, narrow thorax, and distinctive facial features.
camptodactyly-tall stature-scoliosis-hearing loss syndrome (semidominant): Moderate. Camptodactyly-tall stature-scoliosis-hearing loss syndrome is characterized by camptodactyly, tall stature, scoliosis, and hearing loss (CATSHL).
severe achondroplasia-developmental delay-acanthosis nigricans syndrome (autosomal dominant): Moderate.
Cancer hallmarks: proliferative signalling (promotes); escaping programmed cell death (promotes)
Homologues: Orthologues: chimpanzee FGFR3 (96% identical), macaque FGFR3 (95% identical), pig FGFR3 (90% identical), dog FGFR3 (90% identical), mouse Fgfr3 (89% identical), rat Fgfr3 (89% identical), guinea pig FGFR3 (88% identical), tropical clawed frog fgfr3 (74% identical), zebrafish fgfr3 (72% identical). Paralogues in human: FGFR2 (67% identical), FGFR1 (63% identical), FGFR4 (60% identical), KDR (31% identical), FLT4 (30% identical), FLT1 (29% identical), PDGFRB (28% identical), KIT (28% identical), CSF1R (27% identical), PDGFRA (26% identical), TIE1 (25% identical), FLT3 (24% identical), and 41 more.
Diseases named in the same sentence as FGFR3 in open-access papers:
FGFR3 is named in the same sentence as 434 diseases in open-access papers, as found by Europe PMC text mining. Sharing a sentence is not in itself a finding about the gene and the disease. The quoted sentences say what the papers report.
bladder cancer (421 papers, 2005 to 2026). "Erdafitinib is the only FGFRi approved for bladder cancer harboring any of only four point mutations in the FGFR3 extracellular domain (Arg248Cys, Ser249Cys, Gly370Cys and Tyr373Cys)." (PMID 41361008, 2026). "In the context of bladder cancer, FGFR3 mutations and splicing alterations not only drive tumor progression but also shape an immunosuppressive tumor microenvironment." (PMID 41584352, 2026). "Dabogratinib elicited a dose-dependent reduction in downstream signaling across three bladder cancer cell lines harboring an FGFR3 fusion, mutation, or gatekeeper resistance mutation." (PMID 41084837, 2026). "In high CCDC8 expression bladder cancer, the lower frequency of FGFR3 mutations aligns with their more aggressive phenotype." (PMID 39744495, 2025). "In Indian bladder cancer patients, the FGFR3 mutation rate is 19%, comparable to the 15–30% range in European and American populations, but with differences in clinicopathological correlations." (PMID 41514604, 2025). "For example, bladder cancers with Fibroblast Growth Factor Receptor 3 (FGFR3) mutations have shown sensitivity to FGFR inhibitors like erdafitinib, illustrating how genetic data inform therapeutic choices." (PMID 40565559, 2025). "In FGFR3-mutant bladder cancer, concurrent RAS-MAPK activation is associated with a 2.1-fold higher recurrence risk and shorter time to resistance to erdafitinib (3.5 months vs. 5.6 months in wild-type)." (PMID 41438986, 2025). "FGFR3-specific monoclonal antibodies, vofatamab, showed great effectiveness in inhibiting the progression of FGFR3-associated bladder cancer, which provides the potential for the usage of FGFR3 antibodies in treating ACH." (PMID 40256430, 2025). "TERT promoter mutations are present in approximately 55% of bladder cancers across all stages, while FGFR3 mutations are found in 30–50% of cases, often in low-grade, non-muscle-invasive tumors." (PMID 41228219, 2025). "A gender difference is also observed when considering molecular features; for example, there a higher male/female ratio in Fibroblast Growth Factor Receptor 3 (FGFR3)-mutated bladder cancer." (PMID 40364160, 2025). "Tubacin was reported to be effective in bladder cancer where a gene encoding fibroblast growth factor receptor 3 (FGFR3) is mutated and contributes to cancer progression." (PMID 40284485, 2025). "Pemigatinib demonstrated an ORR of 23.9% in FGFR3-mutated bladder cancer patients within the phase II FIGHT-201 trial." (PMID 41438986, 2025). "For example, differential FGFR3 expression has been associated with various malignancies, including bladder cancer and multiple myeloma, where overexpression or activating mutations in FGFR3 contribute to tumor growth and progression." (PMID 40938919, 2025). "It is well established in the literature that luminal bladder carcinomas often arise via a so-called “papillary pathway” (from papillary precursor lesions) and carry characteristic mutations in the FGFR3 gene." (PMID 41003151, 2025). "Fibroblast growth factor receptor 3 (FGFR3) mutations have been implicated in the pathogenesis of both bladder cancer and seborrheic keratoses." (PMID 41158917, 2025). "Erdafitinib is an FDA-approved FGFR inhibitor that has shown significant efficacy against bladder cancer with FGFR3 mutations or translocations." (PMID 39911393, 2025). "CCDC8 expression levels in bladder cancer are significantly associated with the mutation frequencies of various genes, notably FGFR3 and KDM6A." (PMID 39744495, 2025).
bladder cancer (continued). "Across these datasets, we identified 12 potential mutations associated with FGFR3 activation, including notable variants R248C, S249C, Y373C, and G380R, which are most prevalent in bladder cancer but occur infrequently in breast cancer." (PMID 40460005, 2025). "The FGFR3 gene, in particular, has been recognized as an actionable target in bladder cancer, with mutations commonly associated with favorable outcomes in non-invasive cases." (PMID 39761856, 2025). "FGFR3 is frequently altered in UBC, and aberrant activation of FGFR3 has long been implicated in the pathogenesis of bladder cancer." (PMID 39031286, 2024). "For example, mutations in FGFR3 are linked to the development of bladder cancer and multiple myeloma." (PMID 39195304, 2024). "The combination of peptide nucleic acid mediated RT-PCR clamping has been shown to be sensitive enough to detect FGFR3 mutations in bladder cancer from urine sediments, clearly distinguishing mutant DNA from wild-type DNA at concentrations greater than 1%." (PMID 38831455, 2024). "The pan-FGFR inhibitor erdafitinib has shown an overall response rate of 40% in bladder cancer patients whose tumors contained FGFR3 point mutations or FGFR2/3 fusions, leading to FDA approval of this drug in locally advanced or metastatic bladder cancer." (PMID 39031286, 2024). "Aberrantly activated fibroblast growth factor receptor (FGFR)-3 has been implicated in the pathogenesis of bladder cancer." (PMID 39031286, 2024). "We found an increase in FGFR3 associated with a more than two-fold increased risk of bladder cancer in two independent cancer GWAS." (PMID 38684708, 2024). "In these studies, the antitumor activities of FGFR inhibitors have been observed in bladder cancer cells harboring FGFR3 activating mutations, FGFR3 fusions and overexpression." (PMID 39031286, 2024). "FGFR3 inhibitors have shown anti-tumor cell proliferation and pro-apoptotic effects on bladder cancer cells carrying FGFR3 gene mutations, indicating that the status of FGFR3 gene mutations can predict patients’ response to targeted therapy." (PMID 39559360, 2024). "The analysis of data obtained from The Cancer Genome Atlas (TCGA) demonstrated that the presence of targetable mutations in the FGFR3 gene was predominantly observed in bladder cancer." (PMID 38831455, 2024). "In a study on the role of FGFR3 mutations in primary T1 tumors, better progression-free survival was observed among patients with bladder cancer harboring FGFR3 mutations." (PMID 38592174, 2024). "Bladder cancer is associated with FGFR3-BAIAP2L1 fusions, which are known to contribute to the aggressive nature and malignancy of the disease." (PMID 38831455, 2024). "In particular, in recent years, there have been many reports that abnormally increased FGFR3 expression is associated with bladder cancer and is attracting attention as a new therapeutic target." (PMID 38255300, 2024). "The development of therapies targeting specific molecular pathways implicated in bladder cancer progression, such as FGFR3 inhibitors and PARP inhibitors, holds promise for improving treatment outcomes." (PMID 38444854, 2024). "The FDA has granted approval for Infigratinib, Pemigatinib, and Futibatinib in the treatment of cholangiocarcinoma with FGFR2 fusion, as well as Erdafitinib in the treatment of bladder cancer with FGFR3 mutation." (PMID 38831455, 2024). "Higher FGFR3 mRNA and protein expression in bladder cancer are associated with missense mutations of FGFR3." (PMID 38255923, 2024).
bladder cancer (continued). "We present here the first ABM of bladder cancer growth with FGFR3 mutation and an adaptive immune response under combination ICI and targeted therapy." (PMID 38515743, 2024). "The T-cell based subtyping of bladder cancers shows that tumors with high FGFR3 expression are associated with lower T-cell infiltration based on the count of the CD8+ T-cells." (PMID 37151354, 2023). "The overexpression of FGFR3 has been associated with several types of cancer, including bladder cancer, non-small cell lung cancer, and oral cancers." (PMID 37298208, 2023). "Some alterations are more frequently observed in certain cancers, for example, FGFR3 mutations or translocations in bladder cancer, FGFR2 fusions or rearrangements in cholangiocarcinoma, and FGFR1 rearrangements in myeloid/lymphoid neoplasms." (PMID 37000035, 2023). "Abnormal activation of FGFR3 has been recognized to play a cancer‐promoting role in patients with urothelial cancer, especially bladder cancer, in which FGFR3 mutations, rearrangements, and fusions are the most common." (PMID 37750089, 2023). "Activating point mutations in FGFR3 are observed in up to 70% of bladder cancers, with the S249C mutation being the most common point mutation, accounting for 69% of all mutations." (PMID 37924117, 2023). "FGFR3 alterations play an essential role in the immunotherapy for bladder cancer, including amplifications, fusions, and mutations." (PMID 36733484, 2023). "For example, as one of the potential driving oncogenes, FGFR3 point mutations have been detected to be increased in bladder cancer." (PMID 36765337, 2023). "Earlier studies in bladder cancer applied deep learning to infer staging, grade, recurrence risk, FGFR3 mutation, and specific molecular subtypes from histology images." (PMID 37894365, 2023). "For example, the APOBEC3-induced FGFR3 S249C mutation—the most common FGFR3 mutation in bladder cancer—causes constitutive activation of the encoded growth factor receptor to promote cell proliferation." (PMID 36978147, 2023). "In bladder cancer, these somatic changes show a prevalence of up to 85% and, along with FGFR3 mutations at codons 248 and 249, represent the most robust biomarkers for bladder cancer to date." (PMID 37190269, 2023). "FGFR3 somatic mutations are commonly observed in bladder cancer; furthermore, S249C is the most frequently observed mutation, and Y373C is the second most common mutation, with frequencies of 7.3% and 1.9%, respectively, in TCGA-BLCA." (PMID 36831375, 2023). "Previous studies have demonstrated that there is relatively decreased expression of PD-L1 in bladder cancer with FGFR3 mutations or high expression." (PMID 37497216, 2023). "Genes previously shown to be associated with cell proliferation in bladder cancer, such as FGFR3, had significantly lower expression in BKPyV-positive tumors relative to virus-negative tumors." (PMID 36961501, 2023). "Uromonitor, another gene-related biomarker, is capable of detecting minute quantities of TERT promoter and FGFR3 hotspot mutations, common somatic alterations in bladder cancer." (PMID 37762677, 2023). "Other than FGFR3 fusion-positive BC, we also verified that erdafitinib and quisinostat are synergistic in UM-UC-14 bladder cancer cells with FGFR3 S249C activating mutation, which is one of the most prevalent FGFR3 point mutations in BC." (PMID 37479885, 2023). "FGFR3 mutations and overexpression occur more frequently in bladder cancer than any other malignancy, occurring in nearly 80% of the tumors." (PMID 35326568, 2022). "By contrast, high FGFR3 mRNA expression was associated with better progression-free survival in patients with primary pT1 bladder cancer (log-rank, p < 0.001)." (PMID 36142417, 2022). "•In bladder cancers, FGFR3 SVs were significantly associated with CDKN2A/B and TERT alterations, and a lower TMB." (PMID 36462464, 2022).